CYYR1 (cysteine and tyrosine rich 1)
Synonyms: C21orf95
Tractability: Antibody: UniProt predicts a signal peptide or a membrane-spanning region.
Gene: Protein-coding gene on chromosome 21 (26,466,209 to 26,573,286, reverse strand). Ensembl gene ENSG00000166265.
Subcellular location: Membrane
Subcellular location (Human Protein Atlas): Nucleoplasm
Gene Ontology:
Cellular component: membrane
Genetic constraint (gnomAD): Loss-of-function variants: 11 observed, 11.85 expected, observed/expected ratio (o/e) 0.93, 90% interval 0.58 to 1.53. The upper end of that interval is the gene's LOEUF score, 1.53, which puts it in group 6 of 6, group 1 being the genes least tolerant of losing a copy. Missense variants: 202 observed, 198.33 expected, observed/expected ratio (o/e) 1.02, 90% interval 0.91 to 1.14. Synonymous variants: 76 observed, 75.05 expected, observed/expected ratio (o/e) 1.01, 90% interval 0.84 to 1.23.
Homologues: Orthologues: chimpanzee CYYR1 (98% identical), macaque CYYR1 (96% identical), dog CYYR1 (87% identical), pig CYYR1 (86% identical), rabbit CYYR1 (85% identical), mouse Cyyr1 (83% identical), rat Cyyr1 (79% identical), guinea pig CYYR1 (75% identical), tropical clawed frog cyyr1 (70% identical).
Diseases named in the same sentence as CYYR1 in open-access papers:
CYYR1 is named in the same sentence as 14 diseases in open-access papers, as found by Europe PMC text mining. Sharing a sentence is not in itself a finding about the gene and the disease. The quoted sentences say what the papers report.
neuroendocrine tumors (3 papers, 2007 to 2016). "Alterations of sequence and expression of CYYR1 (cysteine/tyrosine-rich 1) were previously observed in neuroendocrine tumors." (PMID 26646589, 2016). "The aim of this study was to analyze the sequence, splicing and expression of the CYYR1 gene in human neuroendocrine tumors." (PMID 17442112, 2007). "The EST database seems to support, for several tissues, a high expression of CYYR1 in some neuroendocrine tumors." (PMID 17442112, 2007). "Analysis of expressed sequence tags revealed high human CYYR1 expression in cells belonging to the diffuse neuroendocrine system, which may be the origin of neuroendocrine tumors." (PMID 23844023, 2013).
breast carcinoma (2 papers, 2016 to 2024). "Our data suggests that CYYR1 drives and/or is associated with a strong reprogramming of transcription in ER+ compared to TN breast cancer samples." (PMID 27846853, 2016). "Finally, we highlight that CYYR1 expression is significantly decreased in breast cancer and is associated with beneficial clinical outcome." (PMID 39059493, 2024). "Moreover, the expression of CYYR1 is decreased in breast cancer samples and low CYYR1 expression is associated with poor prognosis." (PMID 39059493, 2024). "Finally, we found that CYYR1 attenuates anchorage-dependent and independent colony formation of breast cancer cells." (PMID 39059493, 2024). "Moreover, we found that CYYR1 expression attenuates breast cancer cell growth in anchorage-dependent and independent colony formation assays in a PPxY-dependent manner." (PMID 39059493, 2024). "Indeed, analysis of CYYR1 expression in our breast cancer cohort and in the KM plotter database, both reveal that CYYR1 expression is significantly decreased in breast cancer samples compared to normal breast tissue." (PMID 39059493, 2024). "Taken together, our results unprecedentedly highlight a potential protective role of CYYR1 in breast cancer tumorigenesis that could be attributed to its ability to promote WWP1 autoubiquitination and degradation." (PMID 39059493, 2024). "Collectively, these observations suggest that CYYR1 downregulation in breast cancer could favor tumor progression by increasing WWP1 protein." (PMID 39059493, 2024). "While we noticed that very few breast cancer cell lines express CYYR1 mRNA, we were able to confirm its expression in MDA-MB-468 cell lysates by Western blotting using a commercially available CYYR1 antibody that we validated by depleting the cells of CYYR1 with two independent siRNAs." (PMID 39059493, 2024). "Altogether, these results indicate that CYYR1 expression limits anchorage-dependent and independent colony formation of MDA-MB-231 breast cancer cell and that this effect is dependent on its PPxY motifs." (PMID 39059493, 2024). "Conversely, we sought to stably express CYYR1 in MDA-MB-231, a breast cancer cell line that does not express CYYR1." (PMID 39059493, 2024).
Down syndrome (2 papers, 2010 to 2025). "Furthermore, the interplay between CYYR1 and DSCAM leads us to the hypothesis that CYYR1 affects leukemia through Down’s syndrome." (PMID 21044360, 2010).
breast tumors (1 paper, 2024). "Taken together, these data unambiguously show that CYYR1 is associated with beneficial clinical outcome in breast tumors." (PMID 39059493, 2024). "We first determined mRNA levels of CYYR1 in a large cohort of 505 human breast tumors from patients with well-documented follow-up by RT-qPCR." (PMID 39059493, 2024). "Based on our novel findings, we predicted that CYYR1 expression might be downregulated in human breast tumors in comparison to normal breast tissue." (PMID 39059493, 2024). "Strikingly, CYYR1 mRNA levels were strongly decreased in breast tumors, irrespective of the molecular subtype, in comparison to normal breast tissue." (PMID 39059493, 2024).
carcinoid tumor of the lung (1 paper, 2007). "For example, among the 19 CYYR1-related ESTs with "lung" origin, 12 are derived from lung carcinoid, and among the 12 ESTs with "pancreas" origin, 11 are derived from insulinoma." (PMID 17442112, 2007).
colorectal cancer (1 paper, 2025). A primary or metastatic malignant neoplasm that affects the colon or rectum. "CYYR1 (Cysteine and Tyrosine-Rich 1), although less well characterized, has been implicated in the pathogenesis of several malignancies, including breast, ovarian, and colorectal cancers." (PMID 40601653, 2025).
ovarian carcinoma (1 paper, 2025). A malignant neoplasm originating from the surface ovarian epithelium. "CLEC14A has been implicated in tumor angiogenesis and endothelial cell adhesion, while CYYR1 is reportedly dysregulated in several malignancies including breast and ovarian cancers." (PMID 40601653, 2025).
prostate carcinoma (1 paper, 2024). A carcinoma that arises from epithelial cells of the prostate gland. "Because WWP1 has been associated with breast and prostate cancer progression, we sought to investigate the role of CYYR1 in cancer." (PMID 39059493, 2024). "Since WWP1 depletion has been shown to decrease cell growth of breast and prostate cancer cells in similar assays, we speculate that the effect of CYYR1 on cell growth may be mediated by WWP1 degradation." (PMID 39059493, 2024).
tumor (4 papers, 2007 to 2025). "The CYYR1 mRNA isoform expression level was comparable in tumor samples and normal tissues, and a missense mutation was identified in one tumor sample." (PMID 17442112, 2007). "The Aberrant expression of CYYR1 has been associated with tumor progression, suggesting that it may function as an oncogenic factor contributing to tumorigenesis and disease advancement." (PMID 40601653, 2025). "Taken together our study suggests tumor suppressor properties for CYYR1 through regulation of WWP1 autoubiquitination and lysosomal degradation." (PMID 39059493, 2024). "First, the CYYR1 mRNA coding sequence (CDS) was studied in a large series of NE tumors and a P111S mutation in the only neck-derived tumor was identified." (PMID 17442112, 2007). "Indeed, CYYR1 mRNA levels were decreased in breast primary tumors and even more when the primary tumor has metastasized." (PMID 39059493, 2024). "These included cysteine/tyrosine-rich 1 (CYYR1) and LIM domain binding 2 (LDB2) genes that have been recently reported as associated with disease-free survival with higher expression in tumours that metastasized after 24 months vs. tumours that metastasized earlier." (PMID 23526956, 2013). "In order to confirm the presence of two isoforms, an enzymatic digestion of CYYR1 CDS RT-PCR products from normal brain and one NE tumor (sample NE 16) was performed with PstI enzyme, specific for CYYR1 CAG+ isoform digestion." (PMID 17442112, 2007).
cancer (1 paper, 2024). A tumor composed of atypical neoplastic, often pleomorphic cells that invade other tissues. "Most importantly, our study identified a potential protective role in cancer for CYYR1." (PMID 39059493, 2024). "Finally, we observed similar results on CYYR1 by interrogating the publicly available human cancer KM Plotter database that contains gene expression data and survival information." (PMID 39059493, 2024). "Having established a role of CYYR1 in WWP1 degradation, we then set out to explore the role of this novel protein in these cellular processes related to cancer progression." (PMID 39059493, 2024).
CYYR1 also shares sentences with these, for which no sentence is quoted: Alzheimer disease (1 paper); behavioral disorders (1); insulinoma (1); leukemia (1).